TENM3 (teneurin transmembrane protein 3)
Description:
Involved in neural development by regulating the establishment of proper connectivity within the nervous system. Acts in both pre- and postsynaptic neurons in the hippocampus to control the assembly of a precise topographic projection: required in both CA1 and subicular neurons for the precise targeting of proximal CA1 axons to distal subiculum, probably by promoting homophilic cell adhesion. Required for proper dendrite morphogenesis and axon targeting in the vertebrate visual system, thereby playing a key role in the development of the visual pathway. Regulates the formation in ipsilateral retinal mapping to both the dorsal lateral geniculate nucleus (dLGN) and the superior colliculus (SC). May also be involved in the differentiation of the fibroblast-like cells in the superficial layer of mandibular condylar cartilage into chondrocytes.
Synonyms: Ten-3; Ten-m3; KIAA1455; ODZ3; TNM3; TEN3; MCOPCB9; MCOPS15
Tractability: Antibody: UniProt places it where antibodies can reach, with medium confidence; UniProt predicts a signal peptide or a membrane-spanning region; its Gene Ontology location is reachable by antibodies, with medium confidence. PROTAC: ubiquitination databases record sites on it; its protein half-life has been measured.
Gene: Protein-coding gene on chromosome 4 (182,143,918 to 182,803,024, forward strand). Ensembl gene ENSG00000218336.
Subcellular location: Cell membrane; Cell projection, axon
Subcellular location (Human Protein Atlas): Nucleoplasm; Cell Junctions; Cytosol
Gene Ontology:
Molecular function: protein heterodimerization activity; protein homodimerization activity; signaling receptor binding
Biological process: camera-type eye morphogenesis; axon guidance; homophilic cell-cell adhesion; positive regulation of neuron projection development; regulation of homophilic cell adhesion; synaptic membrane adhesion; signal transduction
Cellular component: glutamatergic synapse; membrane; neuron projection; plasma membrane; axon
Genetic constraint (gnomAD): Loss-of-function variants: 59 observed, 240.29 expected, observed/expected ratio (o/e) 0.25, 90% interval 0.2 to 0.31. The upper end of that interval is the gene's LOEUF score, 0.31, which puts it in group 1 of 6, group 1 being the genes least tolerant of losing a copy. Missense variants: 2,905 observed, 3,530.5 expected, observed/expected ratio (o/e) 0.82, 90% interval 0.8 to 0.85. Synonymous variants: 1,290 observed, 1,341.3 expected, observed/expected ratio (o/e) 0.96, 90% interval 0.92 to 1.01.
Homologues: Orthologues: chimpanzee TENM3 (99% identical), macaque TENM3 (99% identical), pig TENM3 (99% identical), guinea pig TENM3 (99% identical), dog TENM3 (99% identical), mouse Tenm3 (98% identical), rat Tenm3 (98% identical), rabbit TENM3 (93% identical), tropical clawed frog tenm3 (92% identical), zebrafish TENM3 (69% identical), Drosophila melanogaster Ten-m (34% identical), Drosophila melanogaster Ten-a (33% identical), and 2 more. Paralogues in human: TENM2 (70% identical), TENM4 (69% identical), TENM1 (59% identical), NAGPA (5% identical).
Diseases named in the same sentence as TENM3 in open-access papers:
TENM3 is named in the same sentence as 38 diseases in open-access papers, as found by Europe PMC text mining. Sharing a sentence is not in itself a finding about the gene and the disease. The quoted sentences say what the papers report.
microphthalmia (6 papers, 2020 to 2025). Congenital or developmental anomaly in which the eyeballs are abnormally small. "Biallelic TENM3 variants were recently reported to cause non-syndromic microphthalmia with coloboma-9 (MCOPCB9) and microphthalmia and/or coloboma with developmental delay (MCOPS15)." (PMID 36911040, 2023). "Two TENM3 variants were identified in a patient with Syndromic microphthalmia 15 in the present study." (PMID 35397152, 2022). "Recessive TENM3 mutations have been identified in syndromic microphthalmia with developmental delay and speech abnormalities, and some cases presenting with intellectual disability." (PMID 35190550, 2022). "Biallelic TENM3 pathogenic variants cause isolated or syndromic microphthalmia." (PMID 35397152, 2022). "Another example is TENM3 (formally ODZ3), which we had proposed as a novel gene for colobomatous microphthalmia based on a single frameshift variant in a multiplex family." (PMID 33456446, 2020).
neuroblastoma (6 papers, 2017 to 2023). Neuroblastoma (NB) is the most common solid, extracranial childhood tumor. "Moreover, recurrent structural changes in the TENM3 gene have been identified in neuroblastoma, and low Ten-3 mRNA levels in these tumors were associated with shorter patient survival." (PMID 28472127, 2017). "Interestingly, in this study, TENM3 was identified as one of the most frequently altered genes, while the chromothripsis that affected the TENM3 gene was found in about 20% of high-risk neuroblastoma." (PMID 33652578, 2021). "In fact, structural alterations of TENM3, including one case of homozygous inactivation, occurred in 5/87 pediatric neuroblastomas and were thus considered recurrent events." (PMID 30618566, 2018). "TENM3 instability in the form of DNA duplication has also been reported by two independent neuroblastoma studies." (PMID 30618566, 2018). "Moreover, in a whole-genome sequence analysis of about 90 neuroblastomas of all stages, a correlation between TENM3 mRNA deregulation and poor patients’ prognosis has been observed." (PMID 33652578, 2021). "Indeed, a significant increase in TENM3 mRNA and protein expression levels was observed when exogenous Wnt3a, a canonical Wnt ligand, is administered to neuroblastoma cells and human colon myofibroblasts." (PMID 33652578, 2021). "The in silico analysis of RNA sequencing data from the TCGA and GTEx projects demonstrates that TENM3 is significantly more highly expressed, as compared to normal tissues, in head and neck squamous cell carcinoma, in pancreatic adenocarcinoma, in thymoma, and in neuroblastoma." (PMID 33652578, 2021). "High TENM3 expression is observed in the human neuroblastoma cell line SH-SY5Y, in which TENM3 is one of the most abundant membrane proteins." (PMID 33652578, 2021). "However, structural aberrations in the TENM3, TENM4 and TENM2 genes were identified in neuroblastoma, and in the case of Ten-4, expression of gene chimeras was demonstrated by RNA-Seq, strongly supporting a functional involvement of these aberrations in tumor development." (PMID 28472127, 2017).
breast carcinoma (3 papers, 2018 to 2021). "The treatment of breast cancer cell lines with indole-3-carbinol, an anti-tumoral agent, is able to down-regulate TENM3 expression, which supports the possible role of TENM3 overexpression in tumor development." (PMID 33652578, 2021). "Moreover, TENM3 was found to be up-regulated in the mammary glands of nulliparous women, who have a higher incidence of breast cancer than parous ones." (PMID 33652578, 2021).
coloboma (3 papers, 2023 to 2025). An abnormality in which a part of a structure in one or both eyes is missing. "Among these were the known human MAC genes TENM3, SMOC1, PAX2, ALDH1A3, and BMPR1B, in addition to NID1, VAX1, and NTN1, which have been previously identified as MAC or coloboma candidates based on animal studies." (PMID 36830662, 2023).
glioma (2 papers, 2018 to 2021). A benign or malignant brain and spinal cord tumor that arises from glial cells (astrocytes, oligodendrocytes, ependymal cells). "Accordingly, TENM3 was classified as a large gene recurrently affected by deletions in low grade glioma in a study that analyzed genomic data derived from 30 tumor types." (PMID 30618566, 2018). "Interestingly, a gene-based query at the Human Protein Atlas displayed a correlation between worst survival and high TENM3 expression in most of the tumors analyzed, including endometrial, lung, ovarian, stomach, thyroid, urothelial cancer and glioma." (PMID 33652578, 2021). "Indeed, TENM3 down-regulation, compared to normal tissues, has been observed in several tumors, including brain lower grade glioma, adrenocortical, colon, rectum, and uterine corpus endometrial carcinomas." (PMID 33652578, 2021).
Hip dysplasia (2 papers, 2022). The presence of developmental dysplasia of the hip. "TENM3 encodes for Teneurin 3, a transmembrane protein, a mutation which has been associated with hip dysplasia." (PMID 35088088, 2022). "Further, TENM3 has been associated with hip dysplasia, suggesting a role in development." (PMID 36553445, 2022).
myopia (2 papers, 2022 to 2025). "TENM3 had been associated with myopia in adults before, whilst the other three loci, MIR4275, LOC101928911 and FAM135B, were novel." (PMID 40410244, 2025). "Several targets of these miRNAs, e.g. GNAS, TRAM1, CTNNB1, EIF4B, TENM3 and RUNX were previously associated with myopia/HM/refractive error in Europeans in genome-wide association studies." (PMID 36685896, 2022). "Also, a GNAS gene was associated with HM, TRAM1, CTNNB1, TENM3 and RUNX with myopia and/or refractive error, and EIF4B with low myopia/hyperopia in Europeans." (PMID 36685896, 2022).
schizophrenia (2 papers, 2022 to 2023). A major psychotic disorder characterized by abnormalities in the perception or expression of reality. "TENM3 is associated with schizophrenia and autoimmune disorders." (PMID 36581688, 2022).
asthma (1 paper, 2022). "Interestingly, five of these loci, i.e., ACTN1, PDS5B, SEMA6D, SPRY4, and TENM3, have been reported of association with the genetic susceptibility of asthma." (PMID 36051697, 2022).
autoimmune disease (1 paper, 2025). A disorder resulting from loss of function or tissue destruction of an organ or multiple organs, arising from humoral or cellular immune responses of the individual to their own tissue constituents. "TENM3 is associated with childhood autoimmune diseases, and the presence of autoantibodies to N-methyl-d-aspartate-receptor subunit-NR1 (NMDAR1), the most common antigen for anti-brain autoantibodies." (PMID 40542392, 2025).
breast ductal carcinomas in situ (1 paper, 2017). "In effect, increased methylation of TENM3 upstream sequences had previously been reported in breast ductal carcinomas in situ, and sequence-based prediction of CpG clusters identified CpG-rich islands surrounding the predicted ATG transcription initiation site in the Ten-4 gene." (PMID 28472127, 2017).
cervical cancer (1 paper, 2018). A primary or metastatic malignant neoplasm involving the cervix. "In addition to HBV, the 4q35.1 locus encompassing part of the TENM3 gene was identified among a list of recurrent integration sites for human papilloma virus (HPV) DNA in cervix cancer cells." (PMID 30618566, 2018).
esophageal cancer (1 paper, 2021). A primary or metastatic malignant neoplasm involving the esophagus. "It is reported that TENM3 was up-regulated in tumor tissues, and it may function as an oncogenic gene in esophageal cancer." (PMID 34416861, 2021).
essential tremor (1 paper, 2017). A relatively common disorder characterized by a fairly specific pattern of tremors which are most prominent in the upper extremities and neck, inducing titubations of the head. "These include a null mutation of TENM3 in microphtalmia and missense mutations of TENM4 in essential tremor." (PMID 28472127, 2017).
glioblastoma (1 paper, 2021). The most malignant astrocytic tumor (WHO grade IV). "Increased TENM3 copy numbers and expressions have also been found in glioblastoma patients with leptomeningeal dissemination, compared to patients who do not present this pattern of metastasization." (PMID 33652578, 2021). "The TENM3 gene has been also identified as a frequent integration site for human papilloma virus DNA in cervix cancer cells, and its hemizygous deletion has been observed in glioblastomas." (PMID 33652578, 2021).
intellectual deficiency (1 paper, 2022). "WGS also localizes the gains insertion site, which is crucial for variant interpretation, as exemplified by our patient with a SHH-KDM4C neo-TAD, or a duplication in TENM3 explaining intellectual deficiency upon disruption of IQSEC2 sequence." (PMID 34744167, 2022).
osteoarthritis (1 paper, 2025). A noninflammatory degenerative joint disease occurring chiefly in older persons, characterized by degeneration of the articular cartilage, hypertrophy of bone at the margins and changes in the synovial membrane. "Several other genes are implicated in DDH but currently have a sparse association with human osteoarthritis in the literature, including BMS1, HOXD9, TBX4, TENM3, and PAPPA2." (PMID 41019141, 2025). "Several other genes implicated in DDH and/or FAI but with a sparse association with human osteoarthritis in the literature, including BMS1, HOXD9, TBX4, TENM3, PAPPA2, and HOXB9, should be further investigated to elucidate their role in osteoarthritis development." (PMID 41019141, 2025).
pancreatic adenocarcinoma (1 paper, 2021). "Although no translocations have been reported for TENM3, a high frequency of TENM3 mutation has been found in skin cutaneous melanoma and pancreatic adenocarcinoma, suggesting that TENM3 may also play a role in carcinogenesis in these tumor types, and in others that have not yet been investigated." (PMID 33652578, 2021).
Syndromic microphthalmia 15 (1 paper, 2022). "Syndromic microphthalmia 15 (MCOPS15, MIM: #615145) is an extremely rare disease caused by homozygous or compound pathogenic variants of the TENM3 gene." (PMID 35397152, 2022).
viral infections (1 paper, 2025). "Tspan7, a transmembrane glycoprotein functionally involved in many different viral infections was downregulated 10 fold, and neuron development genes Tenm3 and Dpysl3 were down 19.4 fold and 26.8 fold respectively in Prol/CJ− vs Prol/Nl cells." (PMID 40434970, 2025).
tumor (7 papers, 2017 to 2023). "TENM3, a member of the conserved Teneurin family, is a highly conserved transmembrane glycoprotein receptor associated with tumor development and drug resistance." (PMID 37214471, 2023). "The possible pro-metastatic role of TENM3 can also be hypothesized in lung tumors in which patients’ circulating tumor cells display TENM3 mutations that are also maintained in metastasis, suggesting that these mutations are important for the migration process." (PMID 33652578, 2021). "Data from different tumor types has suggested that TENM3 may possibly contribute to cancer metastasization." (PMID 33652578, 2021). "Methylation-mediated control of Teneurin expression might thus be constrained to the TENM3 gene or show tumor-dependent differences." (PMID 28472127, 2017). "Additionally, fifteen genes were associated with cancer control; among these, three were related to immunity (MAGT1, RFXANK and SKAP2), two (ADGRL3 and TENM3) were related to cell adhesion, and two (ADAM11 and TEP1) were found to be tumor suppressor genes." (PMID 34107880, 2021).
cancer (3 papers, 2019 to 2021). A tumor composed of atypical neoplastic, often pleomorphic cells that invade other tissues. "Although the majority of the available data hint at an oncogenic role of TENM3 in cancers, an oncosuppresor role cannot be excluded." (PMID 33652578, 2021). "Evidence of its deregulation in different types of cancer has suggested that TENM3 may have a possible functional role in tumorigenesis." (PMID 33652578, 2021).
TENM3 also shares sentences with these, for which no sentence is quoted: developmental delay (3 papers); Alzheimer disease (1); bipolar disorder (1); common variable immunodeficiency (1); hearing loss (1); hyperopia (1); liver cirrhosis (1); lung carcinoma (1); neurodevelopmental disorder (1); ovarian carcinoma (1); refractive error (1); rhabdomyosarcoma (1); skin cutaneous melanoma (1); systemic lupus erythematosus (1); type 1 diabetes mellitus (1); Visual impairment (1).